FTO (FTO alpha-ketoglutarate dependent dioxygenase)
Diseases named in the same sentence as FTO in open-access papers (continued):
Sharing a sentence is not in itself a finding about the gene and the disease.
ovarian carcinoma (continued). "Depletion of FTO in ovarian cancer cells increased m6A modification, which induced ovarian cancer cell proliferation as spheres and promoted cancer stemness phenotype 60." (PMID 34345203, 2021). "In ovarian cancer, downregulated FTO and ALKBH5 induced FZD10 upregulation, which led to reducing PARPi sensitivity." (PMID 34745970, 2021). "To evaluate FTO expression in ovarian cancer, we measured mRNA and protein levels in patient‐derived ovarian cancer tissues and matched control samples, as well as in the normal ovarian epithelial cell line IOSE80 and the ovarian cancer cell line SKOV3, using RT‐PCR and western blot." (PMID 41141648, 2025). "Importantly, we observed a significant downregulation of FTO in ovarian cancer tissues and cell lines, which was closely correlated with increased m6A methylation and enhanced tumor cell aggressiveness." (PMID 41141648, 2025). "In summary, our study supports the hypothesis that FTO plays a critical inhibitory role in the development and progression of ovarian cancer, primarily through its modulation of m6A methylation." (PMID 41141648, 2025). "This analysis revealed FTO as a key candidate, suggesting that its downregulation may contribute to ovarian cancer progression through dysregulation of m6A methylation." (PMID 41141648, 2025). "FTO downregulation elevates global m6A methylation, enhancing ovarian cancer malignancy." (PMID 41141648, 2025). "However, the expression patterns and functional roles of FTO in ovarian cancer remain poorly understood." (PMID 41141648, 2025). "In this context, “readers” such as METTL3 and VIRMA have been associated with apoptosis inhibition, migration, and invasion in ovarian cancer, while FTO leads to reduced “stemness” in ovarian cancer cell lines and YBX1 renders malignant cells susceptible to the cytotoxic effects of cisplatin." (PMID 41301911, 2025). "FTO affects the resistance of ovarian cancer to chemotherapy." (PMID 39175477, 2024). "However, FTO also exhibits a protective role, its downregulation was found in platinum (Pt)‐resistant ovarian cancer cells and forced expression increases sensitivity to Pt in vitro and in vivo." (PMID 38545841, 2024). "Expression of FTO in ovarian cancer varies across studies in different." (PMID 39175477, 2024). "Indeed, METTL3, METTL14, and FTO have been clarified to affect the progression of ovarian cancer in a m6A-dependent manner." (PMID 39617776, 2024). "This is concerning because the existing data only suggest that FTO expression influences the sensitivity of patients with ovarian cancer to chemotherapy, and further evidence from randomized controlled trials offering a higher level of evidence is necessary to substantiate this conclusion." (PMID 39175477, 2024). "FTO is downregulated in ovarian cancer stem cells and tumours." (PMID 38545841, 2024). "Therefore, the role of FTO in ovarian cancer remains controversial, possibly due to the different cancer models." (PMID 38545841, 2024). "The mechanism of action of FTO in ovarian cancer demands further research." (PMID 38545841, 2024). "Meanwhile, other studies indicated that FTO could function as a tumor suppressor and downregulation of FTO promotes cancer development in renal cell cancer, liver cancer and ovarian cancer." (PMID 36874096, 2023). "Moreover, the authors identified two phosphodiesterase genes PDE4B and PDE1C as FTO targets that regulate cAMP signaling and play an important role in maintaining the stemness of ovarian cancer stem cells." (PMID 39872957, 2023). "Furthermore, by reducing the m6A level of 3’UTR and mRNA stability of two phosphodiesterase genes (PDE1C and PDE4B), FTO enhanced second messenger cAMP signaling and inhibited the stemness characteristics of ovarian cancer cells." (PMID 37007161, 2023). "FTO was observed to play tumor-suppressor roles in ovarian cancer and hepatocellular carcinoma." (PMID 36302751, 2022).
ovarian carcinoma (continued). "Interestingly, FTO’s tumor suppressor function was also reported in Ovarian Cancer Stem Cells (OCSCs)." (PMID 35409166, 2022). "However, a study on ovarian cancer showed that the FTO gene inhibited ovarian cancer stem cell self-renewal and tumor initiation." (PMID 35568876, 2022). "However, in ovarian cancer, FTO acts as a tumor suppressor and regulates cyclic AMP signaling involved in stemness and tumor initiation." (PMID 35090515, 2022). "In ovarian cancer, FTO is suggested to suppress self-renewal of ovarian CSCs." (PMID 35859892, 2022). "However, the functional link between FTO and its target genes in epithelial ovarian cancer (EOC) development remains to be elucidated." (PMID 36358640, 2022). "A recent study found that FTO as a m6A regulator could inhibit the self-renewal of ovarian cancer stem cell through blocking cAMP pathway." (PMID 35331183, 2022). "Additionally, FTO was verified to be a tumor suppressor and inhibited the stemness features of ovarian cancer." (PMID 34345203, 2021). "However, in ovarian cancer, FTO functions as a tumor suppressor by restraining cancer stem cell self-renewal." (PMID 34218271, 2021). "However, several other researchers have drawn contradictory conclusions to the effect that FTO played a tumor-suppressing role in ccRCC and ovarian cancer." (PMID 34277426, 2021). "Elevated ALKBH5 expression has also been shown to contribute to the m6A modification of frizzled class receptor 10 (FZD10) mRNA and to the resistance of ovarian cancer cells to treatment with a poly-ADP ribose polymerase inhibitor, which may also be associated with altered FTO levels." (PMID 35251990, 2022). "FTO could block cAMP signaling and inhibit ovarian cancer stem cell self-renewal." (PMID 34345203, 2021). "Moreover, in ovarian cancer, downregulated FTO and ALKBH5 in PARPi resistance cancer cells also could be decreased PARPi sensitivity." (PMID 34745970, 2021). "To further validate the regulatory role of FTO in ovarian cancer progression, we established a subcutaneous xenograft tumor model by injecting SKOV3 cells with either FTO knockout or FTO overexpression constructs into nude mice." (PMID 41141648, 2025). "NNMT was found to be targeted by FTO, which was upregulated and found to demethylate NNMT transcripts in FTO-overexpressing ovarian cancer cells." (PMID 39272943, 2024). "The inhibition of FTO expression notably led to increased proliferation rates and heightened resistance to chemotherapeutic agents like CDDP and PPARi in A2780 ovarian cancer cells, alongside a decrease in apoptotic activity." (PMID 39175477, 2024). "Data from public database Kaplan–Meier Plotter revealed that the expression of FTO and IGF2BF3 was significantly correlated with the prognosis of ovarian cancer patients." (PMID 38714753, 2024). "In epithelial ovarian cancer, CircRNA-AB11FIP1 can increase demethylase FTO level and activate autophagy by altering the m6A level of ATG7 to promote the malignant behavior of ovarian cancer cells." (PMID 36632456, 2023). "FTO and ALKBH5 are downregulated in the PARP inhibitor (PARPi)-resistant ovarian cancer cells compared with parental control, which contributes to PARPi resistance by increasing FZD10 mRNA stability to upregulate the Wnt/β-catenin signaling pathway." (PMID 39872957, 2023). "Recent research revealed that overexpression of FTO was accompanied by BCL-2 upregulation, which was consistent with the trend of regulation of BCL-2 by ALKBH5 found in epithelial ovarian cancer (EOC)." (PMID 36517820, 2022). "In our study, low FTO expression increased the m6A modification of SNAI1 mRNA and promoted SNAI1 expression in ovarian cancer." (PMID 36358640, 2022). "Furthermore, we explored whether FTO suppresses ovarian cancer via its demethylation function." (PMID 36358640, 2022).
ovarian carcinoma (continued). "Overexpression of FTO led to hypomethylation and reduced mRNA stability of two phosphodiesterase genes (PDE1C and PDE4B) but augmented cAMP signaling and dampen stemness features of ovarian cancer cells." (PMID 38714753, 2024). "No change of global m6A levels in ovarian cancer resistant cells might be due to downregulated FTO, ALKBH5, METTL3, and METTL14." (PMID 34745970, 2021).
hepatocellular carcinoma (43 papers, 2018 to 2026). A malignant tumor that arises from hepatocytes. "Reduced FTO nuclear expression has been reported to be associated with poor prognosis in human hepatocellular carcinoma." (PMID 33952279, 2021). "The circGPR137B was reported to act as a sponge for miR-4739 to upregulate its target FTO in hepatocellular carcinoma." (PMID 40712780, 2025). "The circGPR137B/miR-4739/FTO feedback loop can suppress the tumorigenesis and metastasis of hepatocellular carcinoma." (PMID 40986143, 2025). "Knockdown of m6A demethylase Fat Mass and Obesity-associated Protein (FTO), which increased the overall m6A level, inhibited the colony-forming ability of hepatocellular carcinoma cells and improved disease prognosis." (PMID 38798770, 2024). "CircGPR137B/miR-4739/FTO feedback loop suppresses tumorigenesis and metastasis of hepatocellular carcinoma." (PMID 38023219, 2023). "Paradoxically, aberrant expression of the demethylase FTO has also been found in hepatocellular carcinoma (HCC) and predicts poor prognosis." (PMID 37192910, 2023). "FTO can also down‐regulate the m6A level of human hepatoma cells HepG2, reduce mitochondrial content, and increase triglyceride deposition, which provides a new idea for the early prevention of NAFLD." (PMID 39188344, 2023). "In hepatoma cells, FTO knockout significantly reduces the content of new adipogenic enzymes and intracellular lipids." (PMID 35022030, 2022). "Upregulation of FTO has also been reported to facilitate the development of lung adenocarcinoma and hepatocellular carcinoma." (PMID 34378866, 2021). "FTO is also known to inhibit tumorigenesis in hepatocellular carcinoma and intrahepatic cholangiocarcinoma." (PMID 34218271, 2021). "Moreover, studies have shown that FTO expression is upregulated in hepatocellular carcinoma tumors, and targeting the FTO/m6A/GPNMB axis significantly inhibits tumor growth and metastasis while enhancing immune activation." (PMID 39980685, 2025). "The upregulation of FTO in hepatocellular cancer cells promotes cell clonability and survival potential and migration, which may be related to the alteration of m6A methylation." (PMID 41145484, 2025). "In addition, glycoprotein nonmetastatic melanoma protein B (GPNMB), a downstream target of FTO that reduces its m6A abundance, is packaged into small extracellular vesicles (sEVs) derived from hepatocellular carcinoma cells." (PMID 40986143, 2025). "FTO stimulates the development and progression of liver carcinoma, lung cancer, and breast cancer." (PMID 37915034, 2023). "Besides, SIRT1 activated RANBP2, indispensable for FTO SUMOylation at Lysine (K)−216 site, to enhance FTO degradation, leading to progression of hepatocellular carcinoma." (PMID 35945194, 2022). "The m6A eraser FTO has been demonstrated to show tumorigenic features in hepatocellular carcinoma (HCC)." (PMID 37055798, 2023). "Similarly, anonther paper reported that, in hepatocellular carcinoma, FTO could trigger the demethylation of PKM2 mRNA and accelerate the translated production." (PMID 32299393, 2020). "Interestingly, circGPR137B acted as a sponge for miR-4739 to up-regulate its target FTO, which mediated m6A demethylation of circGPR137B and promoted its expression, thus finally forming a feedback loop comprising circGPR137B/miR-4739/FTO axis and affecting the hepatocellular carcinoma cells." (PMID 36614216, 2023). "For example, on the basis of positive regulation of DC function by m6A, researchers have designed nanomedicines containing an FTO inhibitor, and such agents promote DC maturation and antigen presentation after thermal ablation of hepatocellular carcinoma (HCC) cells." (PMID 37485079, 2023). "FTO exerts a protective effect on hepatocellular carcinoma (HCC)." (PMID 36718644, 2023). "In Hepatocellular Carcinoma (HCC), hepatic FTO helps regulate the expression of the gluconeogenic gene." (PMID 35186927, 2022).
hepatocellular carcinoma (continued). "At the same time, FTO demethylates ALDOA transcripts, stabilizing them and promoting their persistence, ultimately leading to the metabolic adaptation of cancer cells to hypoxia, enhancing glycolysis and hepatocellular carcinoma (HCC) progression." (PMID 40102715, 2025).
Hypertension (41 papers, 2011 to 2025). The presence of chronic increased pressure in the systemic arterial system. "A growing number of studies have suggested that genetic variants of FTO are strongly associated with the risk of cardiovascular diseases, including hypertension and acute coronary syndrome." (PMID 37238719, 2023). "Several studies have shown that FTO rs9939609 is associated with the risk of hypertension dependent on BMI in studies with different populations." (PMID 37238719, 2023). "There is evidence that FTO rs9302652 increases the risk of hypertension, which appears to be related to the higher sympathetic modulation of the vasomotor tone in French Canadians." (PMID 37238719, 2023). "A growing number of studies have investigated the effects of FTO gene variations on the risk of hypertension." (PMID 37238719, 2023). "In detail, Kruger and co-workers demonstrated that loss of endothelial FTO protected from HFD-induced hypertension and increases heart rate." (PMID 36672629, 2023). "Current research suggests targeting of 6mA level as novel diagnostic marker and demethylases, AKLBH1, and FTO as potential therapeutic strategy against hypertension." (PMID 35061109, 2022). "In contrary to this, earlier reports found increased m6A levels due to decreased expressed or mutations of another demethylase gene, FTO to be associated with hypertension and cardiovascular diseases." (PMID 35061109, 2022). "To date, several studies have investigated the association between FTO variants and risk of hypertension." (PMID 34675880, 2021). "Of the patients with hypertension, those with FTO rs9939906 AA/AT genotypes were associated with higher LAP and BAI index values." (PMID 31810473, 2019). "Other studies have indicated that FTO variant is associated with increased risk for hypertension through the regulation of sympathetic nervous system." (PMID 26878843, 2016). "In the present study, we investigated the association of FTO and MC4R gene polymorphisms with hypertension in the Chinese Han population and analysed the relationship between FTO rs9939609 and MC4R rs17782313 variants." (PMID 26324055, 2016). "Other studies have indicated that FTO variant is associated with increased risk for hypertension through the regulation of sympathetic modulation of vasomotor tone." (PMID 23977173, 2013). "Associations (all p<0.001) were observed between the FTO variant and increased odds/hazard ratios of ever or incident T2D, ever dyslipidemia, ever metabolic syndrome, and ever hypertension." (PMID 23824655, 2013). "Literature suggested an association of the FTO variants with hypertension or mediation through other hypertension risk factors like BMI or adiposity." (PMID 23691120, 2013). "Taken together, our findings delineate a coherent picture in which AD in working perimenopausal women is driven by a cluster of lipid abnormalities and hypertension, modulated by genetic susceptibility at the FTO locus, and exacerbated by environmental exposures such as smoking." (PMID 41303403, 2025). "The rs9939609 variant has been frequently reported to be correlated with hypertension in children and adolescents, whilst several other intronic polymorphic loci in FTO, such as rs1421085, rs17817449, and rs8050136, have also been reported, although not as often as the rs9939609 polymorphism." (PMID 37375547, 2023). "Thus, the correlation between FTO variants and hypertension risk may be related to the regulation of the sympathetic vasomotor tone." (PMID 37238719, 2023). "In Model 2, arterial hypertension (OR = 2.79, CI: 1.29–6.03, p = 0.009), decreased HDL (OR = 3.27, CI: 1.23–8.64, p = 0.017), and FTO rs9939609 AT/AA genotype showed a significant association with MASLD." (PMID 40864759, 2025). "This newly discovered mechanism provides clear evidence of the involvement of FTO in the regulation of hypertension." (PMID 37238719, 2023).
Hypertension (continued). "Another study reported that FTO rs8050136, rs9939609 and rs9926289, and GNB3 rs1129649 and rs5443 were positively associated with essential hypertension in an Indian population." (PMID 37238719, 2023). "A decrease in FTO expression leads to protection against tachycardia, hypertension, and vascular resistance." (PMID 36536469, 2022). "In FTO knockout mice, a high-fat diet led to glucose intolerance, insulin resistance, and hypertension." (PMID 36536469, 2022). "Although the results are inconsistent, many large studies showed some of FTO genotypes significantly increased risks of hypertension." (PMID 34675880, 2021). "The effects of MC4R and FTO on daytime hypertension were first investigated independently of each other." (PMID 26324055, 2016). "The omnibus global test for both FTO and GNB3 haplotypes showed significant association with hypertension (P<0.0001, each)." (PMID 23691120, 2013). "Interactions between genetic variants of FTO and GNB3 influence clinical parameters to augment hypertension." (PMID 23691120, 2013). "The genes FTO and GNB3 are implicated in essential hypertension but their interaction remains to be explored." (PMID 23691120, 2013). "Interactions between genetic variants of FTO and GNB3 influence clinical parameters to augment hypertension, probably by modulating the FTO expression in metabolically relevant tissues such as the hypothalamus and affecting the subsequent translation of key signaling molecules such as GNB3." (PMID 37238719, 2023). "However, a more pertinent and peripheral mechanism of action for FTO in hypertension has recently been identified." (PMID 35991314, 2022). "FTO protective haplotypes H2: CTGGC and H4: CTGAC interacted with GNB3 protective haplotype Ha: TC to contribute to 1.5- and 2.0-fold lower hypertension susceptibility than the individual protective haplotypes of either gene alone (P = 0.003; P = 6.86E–05, respectively)." (PMID 23691120, 2013). "Common genetic variants of FTO rs9939609 have positive associations with BMI and neck circumference and MC4R rs17782313 in women, but a negative association with diastolic and mean blood pressure in men with hypertension." (PMID 23849767, 2013). "The FTO alleles rs8050136A (P = 0.014), rs9939609A (P = 0.002), rs9926289A (P = 0.015) and the GNB3 alleles rs1129649C (P = 8.76E–06) and rs5443T (P = 9.45E–10) were associated with increased risk of hypertension." (PMID 23691120, 2013). "Upregulation of METTL13 and YTHDF1, and downregulation of FTO and ALKBH5, have been reported in both murine and human adult hypertension-tormented pulmonary arteries and parenchyma." (PMID 35991314, 2022). "As already emphasized, our main aim was to investigate the role of FTO and GNB3 in EH; we adjusted all the results with BMI and other possible confounders to ascertain the direct effect of these genes on hypertension regulation." (PMID 23691120, 2013). "Although our single locus results on FTO and GNB3 were encouraging, however, in a polygenic and multifactorial disease like hypertension, the magnitude of effect is bound to be missed if the genes are examined individually and without considering potential interactions." (PMID 23691120, 2013). "They found that common genetic variants of FTO rs9939609 had positive associations with body mass index and neck circumference and MC4R rs17782313 in women, but a negative association with diastolic and mean BP in men with hypertension." (PMID 36672629, 2023).